SNORD73B (small nucleolar RNA, C/D box U73B)
Synonyms: U73B; RNU73B
Gene: Small nucleolar RNA gene on chromosome 4 (151,102,057 to 151,102,128, forward strand). Ensembl gene ENSG00000201264.
Gene Ontology:
Biological process: RNA processing
Cellular component: nucleolus
Homologues: Orthologues: macaque SNORD73 (92% identical), dog SNORD73B (89% identical), pig SNORD73 (89% identical), rabbit SNORD73B (88% identical), mouse Snord73b (83% identical), tropical clawed frog SNORD73 (75% identical), tropical clawed frog SNORD73 (74% identical), guinea pig SNORD73 (69% identical), rat LOC120103251 (57% identical). Paralogues in human: SNORD73A (68% identical).
Diseases named in the same sentence as SNORD73B in open-access papers:
SNORD73B is named in the same sentence as 1 disease in open-access papers, as found by Europe PMC text mining. Sharing a sentence is not in itself a finding about the gene and the disease. The quoted sentences say what the papers report.
cancer (1 paper, 2024). A tumor composed of atypical neoplastic, often pleomorphic cells that invade other tissues. "Therefore, we believe that SNORD16, SNORD73B, SCARNA4, and SNORD49B are significant contributors to the development and spread of cancer, even if additional study is required to elucidate their potential molecular pathways." (PMID 38311725, 2024).